IL1A (interleukin 1 alpha)
Diseases named in the same sentence as IL1A in open-access papers (continued):
Sharing a sentence is not in itself a finding about the gene and the disease.
COVID-19 (continued). "Due to the attenuated immune response of COVID-19 patients, particularly the reduced upregulation of monocyte CD80 expression and the suppressed release of key cytokines such as IL-6, TNF, IL-1a, and IL-1b, this may lead to a decreased ability to clear C. albicans in these patients." (PMID 38658823, 2024). "The “cytokine storm” hypothesis is further supported by our findings given that an increased level of two powerful pro-inflammatory cytokines, IL-1α and IL-18, were found in fatal, not in non-fatal, COVID-19." (PMID 35386707, 2022). "Interestingly, IDO1 inhibitors suppress the COVID-19-induced pro-inflammatory cytokine release, including TNF-α, IL-6, IL-1α and IL-1β in isolated PBMCs derived from COVID-19-infected rhesus macaques and lower mortality among critically ill patients with COVID-19." (PMID 36589459, 2022). "The levels of Eotaxin, Eotaxin-3 and IL-10 were exclusively elevated in severe SOT COVID-19 whereas IL-16, IL-1RA, IL-1α, MIP-1α and TNF-α, were solely increased in Non-SOT COVID-19 patients with severe disease, as compared to their respective mild/moderate group." (PMID 35075453, 2022). "PCT, ferritin, TNF-α, and IL-1α are molecular mediators of the immune system where concentrations are altered immediately post-trauma and therefore their evaluation at admission is not reliable to predict COVID-19 outcomes in the context of trauma." (PMID 35126355, 2021). "By contrast, we detected a few cytokines (CXCL5, IL-1α/1β/13/17, LF) weakly elevated in asthma groups, which are not relevant to pathogenesis of COVID-19 as the levels of these proteins are not changed or even decreased in general COVID-19 patients." (PMID 34238349, 2021). "As seen in the whole blood transcriptome analysis, leukocytes from COVID-19 patients also demonstrated elevated IL-1β and IL-6 module activity compared with controls, and once again this distinction was not seen in IL1A, IL1B, and IL6 gene expression." (PMID 33319166, 2021). "PIMS-TS children had significantly elevated levels of cytokines, IFNγ, IL-2, TNFα, IL-1α, IFNα, IFNβ, IL-6, IL-15, IL-17A, GM-CSF, IL-10, IL-33 and IL-Ra; elevated chemokines, CCL2, CCL19, CCL20 and CXCL10 and elevated VEGF, Granzyme B and PDL-1 in comparison to COVID-19, seropositive and controls." (PMID 33813138, 2021). "This positive feedback may be activated in severe COVID-19 patients, accelerating NETs and non-canonical pyroptotic interleukin IL-1α production, and inducing respiratory decompensation, DIC, and abnormal immune responses." (PMID 33003552, 2020). "First, we studied the circulating levels of IL-1α, IL-1β, IL-18, IL-15, IL-12p40, IL-12p70, IL-6, IL-27, IL-1Ra, IL-1RI, IL-1RII, IL-6R and sgp130, which are innate proinflammatory cytokines, and their receptors in survivors and non-survivors of severe COVID-19 and healthy controls." (PMID 36142255, 2022). "More so, with neutrophil migration and cell death (IL-1α) contributing much to COVID-19 pathology (Gupta 2020a, b), suPAR can be a better early biomarker than non-specific markers (PCT/CRP) for COVID-19 progression." (PMID 35431536, 2022). "Most COVID-19 patients had either no elevation or only mild increases in the major proinflammatory cytokines including TNF-α, IL-1α, IL-1β, IFN-ɣ, etc.." (PMID 32687484, 2020). "In addition, we could not demonstrate correlation between severity of COVID-19 and other established ARDS-related cytokines such as TNF-α, IL-1α, and IL-1β." (PMID 34938289, 2021).
psoriasis (103 papers, 2008 to 2026). An autoimmune condition characterized by red, well-delineated plaques with silvery scales that are usually on the extensor surfaces and scalp. "The results not only confirmed the effectiveness of treating psoriasis with MTX but also provided the underlying molecular mechanism involving IL-1α." (PMID 38666958, 2024). "Previous research indicated that interleukin-17A (IL-17A), interleukin-22(IL-22), tumor necrosis factor-α (TNF-α), and interleukin-1α (IL-1α) were pro-inflammatory cytokines in psoriasis and linked with NF-κB signalling activation." (PMID 37636269, 2023). "In particular, up-regulation of IL-1R1 via its agonistic ligands consisting of IL-1β and IL-1α is implicated in a variety of human diseases, such as rheumatoid arthritis, psoriasis, type I diabetes, amyotrophic lateral sclerosis, and dry-eye disease." (PMID 35523814, 2022). "We now confirm that induction of S100-alarmins in an imiquimod-induced murine model of psoriasis-like skin inflammation was associated with an increased expression of interleukin (IL)-1α, IL-6, IL-17A, or TNFα." (PMID 33643287, 2020). "Consistently, transgenic overexpression of IL-1α and IL-1 type I receptor in the skin leads to a pathogenic phenotype in mice resembling psoriasis." (PMID 30034395, 2018). "Dysregulation of the IL-1α: IL-1Ra ratio has been implicated in a range of inflammatory skin diseases including psoriasis and contact dermatitis." (PMID 28957335, 2017). "We added psoriasis-associated cytokines of Th1 (TNFα, IL-6, and IL-1α) and Th17 (IL-17 and IL-22) origin to N/TERT1 HEEs during the last three days of the air-liquid interphase culture." (PMID 28928444, 2017). "The importance of IL-1α as a key driver of sterile inflammatory responses is now underlined by a number of clinical trials to target IL-1α in sterile diseases such as psoriasis, type 2 diabetes, and several cancers." (PMID 24790078, 2014). "Therefore, bodyweight reduction through a hypocaloric diet decreases visceral adipose tissue, Leptin, IL-6 and IL-1a while increasing ketone bodies, attenuating inflammatory response linked to psoriasis and obesity." (PMID 35886846, 2022). "Furthermore, normal human keratinocytes show increased expression of IL-1 group mRNA after treatment with psoriasis-associated cytokines (TNFα, IL-1α, IL-17,IL-22)." (PMID 32484435, 2020). "Because our EC data and previous studies have demonstrated that IL-1α and IL-1β contribute to vascular inflammation/atherogenesis, the elevated activity of IL-1 in psoriasis may contribute to this increased risk of atherosclerosis." (PMID 28323859, 2017). "The study assessed the skin surface protein levels of psoriasis patients undergoing whole-body treatment with narrow-band UVB to evaluate whether the levels of the skin surface proteins IL-1α, IL-1RA CXCL-1/2, and hBD-1 were associated with the disease activity and severity measurements." (PMID 36936209, 2023). "Th1 and Th17 cells play a key pathogenic role in psoriasis through the release of several cytokines including tumor necrosis factor alpha (TNF-α), and IL-17A, which, in turn, trigger the release of IL-6 and IL-1α by keratinocytes." (PMID 40046180, 2025). "An in vitro model of psoriasis was established by stimulating keratinocyte HaCaT with a mixture of five pro-inflammatory cytokines (IL-17 A, IL-22, IL-1α, oncostatin M, and TNF-α) (M5)." (PMID 40197419, 2025). "It is widely believed that the ratio of IL1α or IL1β to IL1Ra is a contributing or determining factor in inflammatory diseases, such as polymorphic light eruption, psoriasis and AD 64,72,73." (PMID 39975900, 2025). "A high abundance of IL-1α was observed in psoriatic lesions and overexpression of IL-1α in mice skin was sufficient to induce a psoriasis like phenotype." (PMID 40995100, 2025). "In one study, administering MTX in an in vitro psoriasis model decreased IL-1α release by inhibiting transport mediated by solute carrier family 46 (SLC46)." (PMID 38666958, 2024).
psoriasis (continued). "The heatmaps revealed an increase in several classic proinflammatory cytokines such as Tnf, Il6, Il1a, Il23α and a small number of chemokines, including Ccl19, Ccl20, Cxcl13, and Cxcl5, which are typically elevated in psoriasis patients, in CD169+ macrophages." (PMID 38891893, 2024). "HaCaT cells co‐stimulated with interleukin (IL)‐17, IL‐22, tumor necrosis factor‐alpha (TNF‐α), IL‐1α, and oncostatin M (M5) were used as an in vitro cell model of psoriasis." (PMID 39167035, 2024). "The two most common are utilization of (i) a cytokine cocktail characteristic of psoriasis—IL-17A, IL-22, IL-1α, oncostatin M, and TNFα—so called M5, or (ii) imiquimod." (PMID 38672088, 2024). "Diacerein diminished IL-1α/β-induced gene expression of several cytokines and chemokines, which play an important role in psoriasis." (PMID 36901755, 2023). "Tumor necrosis factor-alpha (TNF-α), interleukin-1 alpha (IL-1α), interleukin-17A (IL-17A), interleukin-22 (IL-22), and oncostatin M (OSM) are closely associated with the pathogenesis of psoriasis." (PMID 36999136, 2023). "Bermekimab, a fully human monoclonal antibody that targets IL-1α, demonstrated significant and encouraging results in patients with hidradenitis suppurativa and psoriasis." (PMID 37511138, 2023). "We further showed induction of CXCL12 in HMEC-1 cells by either mixture of pro-inflammatory cytokines (IL-17A, IL-22, TNF, IL-1α, and oncostatin M), or serum from active psoriasis patients." (PMID 37736772, 2023). "Conversely, urate crystals stimulate keratinocytes to proliferate and produce inflammatory cytokines/chemokines, such as IL-1α or IL-8, indicating the promoting effects of UA on psoriasis." (PMID 36902720, 2023). "A mixture of five inflammatory molecules (TNF-α, IL-1α, IL-17A, IL-22, and oncostatin M; 10 ng/mL each) was used to stimulate HaCaT cells to mimic the microenvironment of psoriasis." (PMID 35209199, 2022). "Then, we verified the results in psoriatic lesions and a psoriasis model in vitro by stimulating keratinocytes with IL-17A, IL-22, IL-1α, oncostatin M, and TNF-α (M5)." (PMID 35586566, 2022). "Murine models have shown that IL-1α is able to initiate spontaneous cutaneous inflammation with histological similarities to psoriasis lesions and to stimulate KCs to induce potent proinflammatory responses." (PMID 36012744, 2022). "It is worthy to point out that the therapeutical effect of AEC-SC on psoriasis-like mice is better than that of IL-1a alone, which need further study." (PMID 35922852, 2022). "We then investigated the effect of curcumol on viability and proliferation of NHEK cells stimulated with a combination of proinflammatory cytokines characteristic for psoriasis (IL-1α, IL-17A, IL-22, oncostatin M, and TNF-α; mix M5)." (PMID 34314383, 2021). "Studies of fecal samples of patients with psoriasis, as well as inflammatory bowel diseases, showed an increased concentration of IL-1α, which is one of the key cytokines involved in the development of inflammation." (PMID 33924414, 2021). "The pathogenesis of psoriasis is extremely complex and involves numerous immune and inflammatory mediators, including IL-1α, TNF-α, IL-17A, and IL-22." (PMID 34314383, 2021). "The psoriasis group tended to have higher concentrations of most analytes in stool (29/47 = 61.7%) and gut IL-1α was significantly elevated (4.19-fold, p = 0.007) compared to controls." (PMID 33117362, 2020). "We chose stimuli known to be relevant in the pathogenesis of psoriasis like IL-17A, IL-17F, TNFα, IL-1α, flagellin as well as murine S100A8 as endogenous Toll-like receptor (TLR)-trigger." (PMID 33643287, 2020). "In psoriasis, IL-1α drives the formation of dermal clusters of T cells and antigen presenting cells and is involved in the development of dermal Th17 responses." (PMID 33117362, 2020). "Levels of gut IL-1α in the psoriasis participants remained significantly unaltered up to 3 months after the first sampling (p = 0.430)." (PMID 33117362, 2020).
psoriasis (continued). "A comparative study between psoriatic transcriptomes and defined expression data from in vitro stimulated keratinocytes showed a large gene expression overlap between IL-1α stimulated keratinocytes (innate immune response) and psoriasis transcriptomes." (PMID 31973112, 2020). "Overexpression of the major epidermal proinflammatory cytokine IL-1α is positively correlated with symptom exacerbation and disease progression in psoriasis, atopic dermatitis, neutrophilic dermatoses, skin phototoxicity and skin cancer." (PMID 32927792, 2020). "IL-1α/β are one of the major inflammatory cytokines from both AD and psoriasis skin lesions, leading to a new concept of ‘‘inflammatory skin march’’." (PMID 32825298, 2020). "Overexpression of IL-1α in basal epidermal layers of transgenic mouse model leads to a psoriasis-like phenotype with keratinocyte hyperplasia and immune cell infiltration." (PMID 31540162, 2019). "Inhibition of IL-1A by secukinumab not only significantly improved psoriatic skin lesions but also reduced pain and subclinical inflammatory lesions in psoriasis patients in the prodromal phase of PsA." (PMID 31349876, 2019). "For instance, several pro‐inflammatory cytokines and arachidonic acid metabolic pathways described to be critical in psoriasis, such as IL‐23, IL‐1α, TNF‐α, TSLP, or PTGS2, were up‐regulated." (PMID 31556482, 2019). "Previous studies have also shown psoriasis macrophages to secrete increased IL-8, IL-1α/β, and TNFα when untreated and this is in agreement with our findings." (PMID 29535706, 2018). "Keratinocyte-derived IL-1α represents an additional inducer of innate immune responses in psoriasis, and it can favor neutrophil and monocyte accumulation during early psoriasis papule formation." (PMID 30034395, 2018). "Then, we proved mS100a7a15, mature IL-1α and calpain-1 were highly expressed in imquimod-induced psoriasis model and mouse IL-17a-neutralizing antibody treatment attenuated mS100a7a15 expression." (PMID 28060905, 2017). "It is thought that targeting IL-1α holds significant promise as a unique therapeutic option for psoriasis and a variety of other diseases." (PMID 28060905, 2017). "In psoriasis lesions, neutrophils accumulate and reinforce cytokine cascades by releasing IL-1α, IFN-α and TNF." (PMID 24260178, 2013). "Overexpression of IL-1α in basal epidermis in transgenic mice initiates a psoriasis-like cutaneous inflammation." (PMID 18576390, 2008). "Furthermore, KCs stimulated by a combination of psoriasis-associated cytokines (TNF-α, IL-1A, IL-17A, IL-22, and oncostatin M) activate autophagic flux, which leads to recurrent psoriasis inflammation and increased skin barrier damage." (PMID 38606161, 2024). "To further investigate whether Gpr15lg can regulate immune response in psoriasis, we detected the level of IL-1α, TNF-α, IL-1β and S100A7 by qRT-PCR and IHC." (PMID 38393364, 2024). "Also, IL-36α expression was induced by IL-1α, and then acted via a feedback loop to induce IL-1α; thus, the two cytokines appear to cooperate to promote psoriasis-like dermatitis in mice." (PMID 38077370, 2023). "Furthermore, we used a psoriasis-associated cytokine mixture (Pso Mix) (IL-17, TNF-α, IL-1α, OSM and IL-22) to stimulate primary KCs to mimic the psoriatic profile." (PMID 37497003, 2023). "In this study, we used HaCaT keratinocytes stimulated with M5, a cocktail of five inflammatory cytokines (TNF-α, oncostatin M, IL-1α, IL-17A, and IL-22), as an in vitro model of psoriasis with typical upregulation in the production of cytokines, chemokines, and antimicrobial peptides." (PMID 36555642, 2022). "Although the exact physiological concentrations of hBDs are not well known, the doses of hBD-2 have been estimated to be 3.5–16 μM (15–70 μg/mL) in IL-1α-stimulated epidermal cultures and approximately 20 μM (87 μg/mL) in skin tissues from patients with psoriasis." (PMID 35955934, 2022).
psoriasis (continued). "Even though decreased icIL-1Ra1 expression has been detected in lesional psoriatic skin compared to uninvolved psoriatic or normal skin, an increased ratio of icIL-1Ra1 to IL-1α, mainly due to the reduction of IL-1α, has been reported in human inflammatory skin diseases, including psoriasis or AD." (PMID 33796114, 2021). "Inflammatory skin conditions like psoriasis are linked to elevated levels of both IL-1a and S100A7 (also known as psoriasin) and an increased signalling axis composed of NF-κB/p38MAPK/Caspase-1/IL-1a, which regulates S100A7." (PMID 34203393, 2021). "Future mechanistic studies may clarify the exact mechanisms involved; meanwhile, our finding of enhanced IL-1α, a key regulator of inflammatory processes, suggests that the gut may play a central role in the induction of inflammatory responses in psoriasis." (PMID 33117362, 2020). "In addition, IL-1α expression is decreased, whereas IL-1β expression is increased in the lesional skin of psoriasis patients." (PMID 32194991, 2020). "While the relatively small sample size is an important limitation of the study, this limitation was partially overcome by repeated cytokine measures, which confirmed, in particular, the consistently high levels of IL-1α in the psoriasis individuals compared to the controls." (PMID 33117362, 2020). "Importantly, in a mouse model of psoriasis, calpain-1 inhibition improved epidermal hyperplasia, alleviated skin inflammation and reduced the expression levels of mature IL-1α and calpain-1." (PMID 28060905, 2017). "Importantly, mature IL-1α and calpain-1 expression were decreased in the psoriasis-like lesions in the treatment of PD151746." (PMID 28060905, 2017). "It has been showed that IL-1α, IL-1β, IL-17A and IL-23 are important to psoriasis progress." (PMID 28060905, 2017). "Since IL-1α and IL-1β have been shown to contribute to vascular inflammation and atherosclerosis, the increased levels of serum IL-1 noted in psoriasis may be responsible for promoting atherosclerosis." (PMID 28323859, 2017). "Also, mS100a7a15, calpain-1 and mature IL-1α protein levels were induced in psoriasis-like skin compared to normal skin." (PMID 28060905, 2017). "Besides, cytotoxicity and IL-1α release assays indicate that DHNA causes less irritation problems than dithranol, which is commonly employed to treat psoriasis in many countries." (PMID 23690852, 2013). "In psoriasis, IL-1ra and IL-1RII were both significantly overexpressed in the suprabasal and basal compartment, respectively, and inversely correlated with the expressions of IL-1α." (PMID 23847621, 2013). "Similarly, EGFR signaling through MEK1/2 and p38 kinase synergizes with IL-1α in the skin innate immune response by enhancing the production of antibacterial peptides in normal skin and chronic inflammatory diseases like psoriasis." (PMID 23878744, 2013). "In addition, IL-17A, SOM, and IL-1α are major inflammatory factors contributing to psoriasis." (PMID 38607144, 2024). "In psoriasis, MIR31HG was found to be elevated in psoriasis lesions and the upregulation of MIR31HG required IL-17A, IL-22, TNF-α, and IL-1α stimulation, demonstrating that nuclear factor kappa B inhibitor (NF-κB) signalling could be crucial crosstalk in psoriasis." (PMID 37636269, 2023). "Therefore, increased IL-1α expression in the intestinal lumen of patients with psoriasis may be the link between the inflammation of the intestines accompanying this dermatosis and skin lesions." (PMID 33924414, 2021). "However, looking on the effects of cytokines highly relevant in the pathogenesis of psoriasis, i.e., IL-17A, IL-17F, IL-1α, or TNF, on S100A8 or S100A9 expression in keratinocytes we found strong effects on mRNA induction for both genes most pronounced for IL-17A > IL-17F > IL-1α > TNF." (PMID 33643287, 2020). "However an increase of secreted IL-1α in lesional skin of psoriasis patients was observed." (PMID 23531535, 2013).